EGF (epidermal growth factor)
Description:
EGF stimulates the growth of various epidermal and epithelial tissues in vivo and in vitro and of some fibroblasts in cell culture. Magnesiotropic hormone that stimulates magnesium reabsorption in the renal distal convoluted tubule via engagement of EGFR and activation of the magnesium channel TRPM6. Can induce neurite outgrowth in motoneurons of the pond snail Lymnaea stagnalis in vitro.
Synonyms: HOMG4; URG
Tractability: Antibody: its Gene Ontology location is reachable by antibodies, with high confidence; UniProt predicts a signal peptide or a membrane-spanning region. PROTAC: ubiquitination databases record sites on it.
Target class: Secreted protein
Gene: Protein-coding gene on chromosome 4 (109,912,883 to 110,013,766, forward strand). Ensembl gene ENSG00000138798.
Subcellular location: Membrane
Pathways (Reactome):
Signal Transduction: Downregulation of ERBB2 signaling; EGFR downregulation; EGFR interacts with phospholipase C-gamma; ERBB2 Activates PTK6 Signaling; ERBB2 Regulates Cell Motility; Estrogen-dependent nuclear events downstream of ESR-membrane signaling; Extra-nuclear estrogen signaling; GAB1 signalosome; GRB2 events in EGFR signaling; GRB2 events in ERBB2 signaling; NOTCH3 Activation and Transmission of Signal to the Nucleus; PI3K events in ERBB2 signaling; PI5P, PP2A and IER3 Regulate PI3K/AKT Signaling; PIP3 activates AKT signaling; PLCG1 events in ERBB2 signaling; RAF/MAP kinase cascade; SHC1 events in EGFR signaling; SHC1 events in ERBB2 signaling; Signaling by EGFR; Signaling by ERBB2; Signaling by ERBB4
Disease: Constitutive Signaling by Aberrant PI3K in Cancer; Constitutive Signaling by EGFRvIII; Constitutive Signaling by Ligand-Responsive EGFR Cancer Variants; Inhibition of Signaling by Overexpressed EGFR; Signaling by ERBB2 ECD mutants; Signaling by ERBB2 KD Mutants; Signaling by ERBB2 TMD/JMD mutants
Developmental Biology: Developmental Lineage of Mammary Gland Luminal Epithelial Cells; Developmental Lineage of Mammary Gland Myoepithelial Cells; Developmental Lineage of Multipotent Pancreatic Progenitor Cells; Differentiation of Keratinocytes in Interfollicular Epidermis in Mammalian Skin
Vesicle-mediated transport: Cargo recognition for clathrin-mediated endocytosis; Clathrin-mediated endocytosis
Cellular responses to stimuli: NFE2L2 regulating tumorigenic genes
Hemostasis: Platelet degranulation
Gene Ontology:
Molecular function: growth factor activity; guanyl-nucleotide exchange factor activity; protein binding; receptor ligand activity; transmembrane receptor protein tyrosine kinase activator activity; epidermal growth factor receptor binding; calcium ion binding
Biological process: angiogenesis; epidermal growth factor receptor signaling pathway; ERBB2-EGFR signaling pathway; ERK1 and ERK2 cascade; negative regulation of secretion; positive regulation of canonical Wnt signaling pathway; positive regulation of cell migration; positive regulation of cell population proliferation; positive regulation of DNA-templated transcription; positive regulation of endothelial cell migration; positive regulation of endothelial cell proliferation; positive regulation of epithelial tube formation; positive regulation of gene expression; positive regulation of hyaluronan biosynthetic process; positive regulation of MAPK cascade; positive regulation of mitotic nuclear division; positive regulation of peptidyl-threonine phosphorylation; positive regulation of phosphatidylinositol 3-kinase/protein kinase B signal transduction; positive regulation of phosphorylation; positive regulation of protein localization to early endosome; positive regulation of receptor internalization; regulation of calcium ion import; regulation of protein localization to cell surface; positive regulation of DNA binding; regulation of receptor signaling pathway via JAK-STAT; and 3 more
Cellular component: extracellular exosome; extracellular region; lysosomal membrane; clathrin-coated endocytic vesicle membrane; plasma membrane; platelet alpha granule lumen; membrane
Genetic constraint (gnomAD): Loss-of-function variants: 90 observed, 144.77 expected, observed/expected ratio (o/e) 0.62, 90% interval 0.52 to 0.74. The upper end of that interval is the gene's LOEUF score, 0.74, which puts it in group 3 of 6, group 1 being the genes least tolerant of losing a copy. Missense variants: 1,300 observed, 1,538.9 expected, observed/expected ratio (o/e) 0.84, 90% interval 0.81 to 0.88. Synonymous variants: 502 observed, 536.33 expected, observed/expected ratio (o/e) 0.94, 90% interval 0.87 to 1.01.
Gene-disease validity (ClinGen):
ClinGen rates the evidence that EGF causes each of these diseases.
renal hypomagnesemia 4 (autosomal recessive): Limited.
Homologues: Orthologues: chimpanzee EGF (99% identical), macaque EGF (94% identical), rabbit EGF (78% identical), dog EGF (78% identical), pig EGF (77% identical), guinea pig EGF (70% identical), rat Egf (67% identical), mouse Egf (66% identical), tropical clawed frog egf (42% identical), zebrafish egf (36% identical), Drosophila melanogaster Lrp4 (21% identical), Caenorhabditis elegans rme-2 (15% identical). Paralogues in human: LRP1B (23% identical), LRP1 (23% identical), LRP2 (22% identical), LRP8 (16% identical), LRP4 (15% identical), VLDLR (15% identical), LRP6 (14% identical), NID1 (14% identical), LRP5 (14% identical), NID2 (14% identical), LRP3 (8% identical), and 2 more.
Diseases named in the same sentence as EGF in open-access papers:
EGF is named in the same sentence as 703 diseases in open-access papers, as found by Europe PMC text mining. Sharing a sentence is not in itself a finding about the gene and the disease. The quoted sentences say what the papers report.
breast carcinoma (1,014 papers, 1986 to 2026). "They showed that EGF signaling induces PD-L1 N-linked glycosylation and stabilizes PD-L1, which plays a role in breast cancer cell immunosuppression." (PMID 38474186, 2024). "In particular, TAMs overexpress growth factors such as vascular endothelial growth factor and EGF, which are highly associated with the metastatic spread of tumor cells in human breast cancer." (PMID 35216272, 2022). "Upon epidermal growth factor (EGF) stimulation, p66Shc and Grb-2 potentiate cell proliferation, invasion, and migration in breast cancer cells by associating with small GTPases ARF-1 and ARF-6; and coordinating their activation." (PMID 35273919, 2022). "In the control experiments, EGF treatments induced K63-linked ubiquitination of TWIST1 in the BT549 breast cancer cell line." (PMID 36115849, 2022). "SRGN expression was also found to be induced in the epithelial breast cancer cell line SK-BR-3 through induction of EMT by EGF, which demonstrates the strong association between serglycin and EMT, both in normal as well as in cancer cells." (PMID 35494005, 2022). "Breast cancer-related EGF stimulation is strongly associated with poor prognoses and mediates invadopodia precursor formation in breast cancer cells." (PMID 34440749, 2021). "The cytotoxicity of EGF-modified PMBN-paclitaxel complexes (EGF-PMBN-PTX) was evaluated in the EGFR-overexpressed or -deficient BT-20 breast cancer cell line, A431 squamous carcinoma cell line, and H69 small cell lung cancer cell line." (PMID 33530291, 2021). "Cofilin 1 (CFL1) is an intracellular actin-modulating protein associated with EGF-stimulated chemotaxis and invadopodia localization in breast cancer cell invasion." (PMID 33267867, 2020). "Further, EGF overexpression is observed in all subtypes of breast cancer and has been shown to be associated with larger tumor size, poor differentiation, and poor outcomes." (PMID 32164769, 2020). "In breast cancer, dacinostat (HDACi) disrupted epidermal growth factor (EGF)-mediated signaling, which is associated with increased metastasis and cell survival." (PMID 32670880, 2020). "In vivo mammary tumors’ treatment with EGF-conjugated GNPs associated with laser irradiation showed a macroscopic tumor reduction and an increased hemorrhagic area." (PMID 33353068, 2020). "Epidermal growth factor (EGF) from breast cancer-associated MSCs promote mammosphere formation via the PI3K/Akt signaling pathway." (PMID 31130595, 2019). "Breast cancers that express epidermal growth factor (EGF) receptors (EGFRs) are associated with poor prognosis." (PMID 31532771, 2019). "Our results from PIP5Kα‐deficient and ‐reconstituted breast cancer cells supported that PIP5Kα positively mediates breast cancer cell proliferation and epidermal growth factor (EGF)‐induced Akt activation." (PMID 29851245, 2018). "Resveratrol treatment of breast cancer MDA-MB231 cells caused inhibition of the epidermal growth factor (EGF)-induced elevation of cell migration, and of the expression of MMP-9." (PMID 29194365, 2017). "Inhibition of Rac1 by ZINC69391 was also associated with reduced epidermal growth factor (EGF)-mediated Rac1 activation and efficient inhibition of cell proliferation, cell cycle progression and cell migration in highly metastatic breast cancer cell lines." (PMID 27442895, 2017). "TOB1 is regulated by EGF-Dependent HER2 and EGFR signaling and TOB1 protein expression and phosphorylation is associated with EGF-dependent erbB signaling and proliferation in breast cancer." (PMID 27506935, 2016). "Overall, our findings suggest that the migratory phenotype of breast cancer cells, is linked to the activation of EGFRs and further demonstrates successful delivery of EGF to the cells within the 3D microfluidic device." (PMID 27678304, 2016). "Prolactin and EGF and their receptors were found to be associated with breast cancer progression and to enhanced MCF7 and T47D cell proliferation." (PMID 27564112, 2016).
breast carcinoma (continued). "EGF is known to be a growth factor that causes leading edge protrusions, an early event in migration of breast cancer cells." (PMID 26055698, 2015). "Inhibition of EGF signaling in Her-2-positive breast cancer has been associated with glucose deprivation and energetic stress." (PMID 25605021, 2015). "qRT-PCR was performed to assess expression levels of EREG, AREG, EGF, HB-EGF and TGFα, all of which have been implicated in breast cancer." (PMID 26215578, 2015). "Consistently, in the present study, re-expression of the phosphor-mimicking mutant Anxa2 (Anxa2 Y23D), but not the phosphorylation-deficient Anxa2 (Anxa2 Y23A), in Anxa2-silencing breast cancer cells rescued EGF-induced EMT." (PMID 26307676, 2015). "The divergence of signalling for EMP regulation between EGF and hypoxia that we characterise here is of therapeutic importance, particularly bearing in mind associations in breast cancer patients between EMT, poor prognosis and treatment resistance." (PMID 25975820, 2015). "The epidermal growth factor (EGF) family of ligands has been implicated in promoting breast cancer initiation, growth and progression." (PMID 26215578, 2015). "Arf6 is well characterized in the EGF pathway, which has been associated with breast cancer invasion." (PMID 25779663, 2015). "Taken together, our study demonstrated that Arf6 activation plays a potential role in EGF-induced E-cadherin internalization, providing new mechanism underlying the effect of Arf6 on promoting breast cancer cell metastasis." (PMID 25678857, 2015). "Several EGF ligands have been implicated in breast cancer, including EGF, epiregulin (EREG), amphiregulin (AREG), heparin-bound EGF (HB-EGF) and transforming growth factor alpha (TGFα)." (PMID 26215578, 2015). "On the other hand, proliferation stimulation was observed in hepatocytes, in which AnxA1 was related to EGF, and in breast cancer; in the latter, it was associated with formyl peptide receptor (FPR2) binding and increased levels of cyclin D1." (PMID 24719523, 2014). "EGF “like” ligands are largely implicated in breast cancer progression, yet, most reports have only studied the expression of ligands specific to EGFR, or those specific to HER3." (PMID 25249538, 2014). "Nevertheless, the IGF1 and EGF are stimuli to migration of cancer cells to distant areas, to form metastasis, and have been implicated in the development and progression of human breast carcinoma." (PMID 24591761, 2014). "Here we have tracked the intracellular dynamics of PTPD1 in cells derived from breast cancer, an example where EGF signalling is linked to carcinogenesis." (PMID 25062045, 2014). "The Giα proteins associated with RTKs, Gab1, FRS2 and Shp2 in breast cancer cells and their ablation impaired Gab1’s interactions with Shp2 in response to EGF and IGF-1, or with FRS2 and Grb2 in response to bFGF." (PMID 24521094, 2014). "The IL-8 pathway was reported to be important in cancer and CX3CL1 expression was associated with a poor outcome in breast cancer patients as it promotes breast cancer via transactivation of the epidermal growth factor pathway." (PMID 25521548, 2014). "Locally advanced breast cancers are often associated with higher expression of growth factors EGF, VEGF that are associated with shorter relapse free survival or over-all survival and aggressiveness of the disease." (PMID 24138843, 2013). "In this study we show that EGF-induced EMT in MDA-MB-468 breast cancer cells is associated with a reduction in agonist-stimulated and store-operated Ca2+ influx, and that MDA-MB-468 cells prior to EMT induction have a high level of non-stimulated Ca2+ influx." (PMID 22666335, 2012). "Previous studies in prostate and breast cancers demonstrated that EGF induced AR/ER/Src association, resulting in activation of Src signaling and that Src signals phosphorylated tyrosine residue of AR, provoking its transactivation and cell proliferation." (PMID 22922989, 2012).
breast carcinoma (continued). "This suggested that restoring EBP50 expression in EBP50 deficient MDA-MB-231 cells inhibited EGF-induced breast cancer cell proliferation." (PMID 22476347, 2012). "In hormone-responsive cells expressing both AR and ER (α and/or β), such as prostate and breast cancers, AR/ER/Src association plays a crucial role in activation of Src signals triggered by EGF and/or sex hormones." (PMID 22922989, 2012). "We cloned the Brn-3b promoter, mapped the transcription start site and showed stimulation by estradiol and growth factors, nerve growth factor and epidermal growth factor, which are implicated in breast cancer initiation and/or progression." (PMID 21241485, 2011). "Increased Brn-3b expression via growth factors such as NGF and EGF or the hormone, estradiol, which are implicated in enhancing the growth of breast cancer cells, are likely to be are propagated by autoregulation." (PMID 21241485, 2011). "To investigate this effect further we examined the differential response and mechanism of ATP signaling associated with EGF-mediated EMT in MDA-MB-468 breast cancer cells." (PMID 21850275, 2011). "We located a region in ESR1 which showed a moderate signal for association with breast cancer risk, but were unable to link common variation in the EGF gene with breast cancer aetiology or prognosis." (PMID 18271972, 2008). "We selected haplotype-tagging SNPs (tagSNPs) spanning the ESR1 and EGF genomic regions and assessed their association with breast cancer risk, the Nottingham Prognostic Index (NPI) and breast cancer survival." (PMID 18271972, 2008). "Our results do not support a strong association between common variants in the ESR1 and EGF genes and breast cancer risk, tumour characteristics or survival." (PMID 18271972, 2008). "We sought to determine if common genetic variation in the ESR1 and EGF genes affects breast cancer risk, tumour characteristics or breast cancer survival." (PMID 18271972, 2008). "We analysed common genetic variation in the ESR1 and EGF genes in relation to breast cancer risk, tumour characteristics and breast cancer survival using a comprehensive haplotype tagging analysis." (PMID 18271972, 2008). "We predict that breast cancer cells treated with ATZ alone should have a greater proliferation rate associated with stronger EGF signaling activity, while the co-treatment of ATZ+antagonist and ATZ+Curcumin should produce limited proliferation and diminished EGF signaling activity." (PMID 40771272, 2025). "EGF/EGFRs directly stimulate the formation of tumor blood vessels by regulating the expression of genes, thereby further accelerating the invasion and spread of tumors, and are associated with many types of cancers such as breast cancer (BC) and OC." (PMID 40251641, 2025). "Furthermore, IORT changes the expression of miRNA223, thereby reducing EGF expression and EGF receptor activation, a cascade that normally inhibits the growth of breast cancer cells and decreases the risk of local tumor recurrence in mice models." (PMID 35681234, 2022). "RGS16 overexpression in breast cancer cells inhibits the cell prolife ration dependent on epidermal growth factor (EGF), and decreased RGS16 expression was associated with a reduction in the cell proliferation rate and an increased resistance to tyrosine kinase inhibitors." (PMID 35453754, 2022). "We further investigated the underlying mechanisms of the activation of EGF signaling by PN-1 in breast cancer cells and demonstrated that PN-1 could prevent extracellular EGF proteolytic cleavage by HtrA1 through binding and blocking HtrA1." (PMID 31501409, 2019). "N-WASP was implicated in chemotaxis of breast cancer cells toward EGF and in macrophages, but the mechanisms are unknown." (PMID 31668663, 2019). "Our mechanistic study revealed that PBX1 controls the expression of a subset of ERα target genes stimulated by EGF in vitro and may be linked to breast cancer progression." (PMID 26215677, 2015).